GATA6 (GATA binding protein 6)
Diseases named in the same sentence as GATA6 in open-access papers (continued):
Sharing a sentence is not in itself a finding about the gene and the disease.
tumor (continued). "Computed tomography (CT) analysis revealed significantly lower tumor burdens in lungs of GATA6-overexpressing KC mice (referred to as KC-G) than in Control KC mice (referred to as KC-C)." (PMID 32596145, 2020). "Pathway analysis showed activation of the transforming growth factor-β pathway in YSTs, which is associated with the overexpression of GATA6 and FOXA2 and the hypermethylation of tumor-suppressor genes (e.g., RASSF1, RUNX3, HIC1, or APC)." (PMID 32999426, 2020). "GATA6, a zinc-finger transcription factor, functions as a tumor promoter or suppressor depending on the type of tumor." (PMID 33173435, 2020). "Due to the limitation of this study, we cannot exclude the possibility that GATA6 impacted tumor growth through modulating differentiation of tumor cells." (PMID 32596145, 2020). "The classical group was enriched in SMAD4 and GATA6, while the basal subtype was molecularly similar to basal tumours in bladder and breast cancer." (PMID 33371431, 2020). "This led us to postulate that GATA6 is a tumour suppressor during sebaceous carcinogenesis, likely through controlling DNA mismatch repair response mechanisms." (PMID 33082341, 2020). "We found comparable GATA6 mRNA level between tumor samples and cancer cell lines, which was consistently lower than that of para-tumoral tissues." (PMID 32596145, 2020). "GATA6 promotes tumour progression and acts as an oncoprotein in gastric cancer, colorectal cancer, breast cancer and cutaneous T-cell lymphoma, but it suppresses tumour progression in astrocytoma and hepatocellular carcinoma." (PMID 33060563, 2020). "Further analysis showed the frequent reduction of GATA6 expression in intestinal-type tumors than the diffuse- type tumors when compared to their corresponding non-tumor tissues (p = 0.0095 and p = 0.0142, respectively)." (PMID 32704077, 2020). "In line with our in vitro findings, IHC staining revealed that DOX treatment resulted in overexpression of GATA6 in tumor cells of xenograft." (PMID 32596145, 2020). "For instance, suppression of Gata6 sensitized tumor cell organoids to BMP-mediated growth inhibition." (PMID 32157212, 2020). "Ablation of Gata6 in K14ΔNLef1 mice (K14ΔNLef1:cKO) resulted in an increased rate of tumor formation following DMBA treatment, and in an increased number of tumors per mouse, indicating that Gata6 acted as a tumor suppressor." (PMID 30886049, 2019). "Our data indicate that Gata6 is likely to be responsible for the sebaceous differentiation observed in the tumors but also acts as a tumor suppressor." (PMID 30886049, 2019). "These discrepancies further support the idea of a complex role of GATA6 in tumor progression and strongly suggest that the role of GATA6 in cancer is stage- and context-dependent." (PMID 30674866, 2019). "In contrast, a tumor suppressive role of GATA6 in cetuximab resistance was demonstrated by decreasing the expression of MIR100HG26." (PMID 30674866, 2019). "Gata6 mRNA and protein expression levels were similar between pResMφ from control and tumor-bearing mice." (PMID 29920191, 2018). "We propose that GATA6 belongs to a new type of cancer genes whose effect can be oncogenic or tumour-suppressive depending on the cellular/genomic context." (PMID 27325420, 2017). "We provide mechanistic insight into GATA6 tumour-suppressive function, its role as a regulator of canonical epithelial differentiation, and propose that loss of GATA6 expression is both prognostic and predictive of response to adjuvant therapy." (PMID 27325420, 2017). "Here, we show that the same is true for PDAC cells, where GATA6 downregulation increased tumour cell dissemination." (PMID 27325420, 2017). "Consistently, GATA6 was significantly lower in BAS-L tumours (p<0.001), and GATA6-silenced PaTu8988S cells ectopically expressed the basal keratins KRT5 and KRT14." (PMID 27325420, 2017). "Classical tumours showed high GATA6 mRNA expression, and patients had a significantly better outcome." (PMID 27325420, 2017).
tumor (continued). "Concertedly, these findings contribute to explain the conundrum generated by observations supporting that GATA6 acts as oncogene in PDAC; yet, patients with GATA6-low tumours have worse outcome." (PMID 27325420, 2017). "To improve the usefulness of these markers in the clinic and to determine which cells express GATA, we determined protein expressions of GATA3 and GATA6 on paraffin-embedded tumour samples using standard immunohistochemical techniques." (PMID 29038332, 2017). "Consistently, in the ESPAC-3 patient cohort, low GATA6 expression correlated with moderate/poor tumour grade." (PMID 27325420, 2017). "One sample having a miR-196b upregulation (~2-fold) displayed instead a more intense GATA6 expression in tumour tissue than in normal colonic mucosa." (PMID 27902469, 2017). "Our results furthermore suggest a role of miR-196b expression in CRC, as an antagonist of GATA6 function in tumor cells, thus providing the basis for a potential targeting strategy for the treatment of CRC." (PMID 27902469, 2017). "Transcriptional changes were extensively studied in both conditions and revealed that a loss of acinar specific transcription factors, such as Gata6, Mist1 and Ptf1a, supports ADM formation and, in presence of mutant Kras, tumor development." (PMID 26716510, 2016). "The determination of epigenetic modifications of the Gata6 promoter in acinar cells, 3D-ADMs and tumor cells showed a persistent and strong enrichment of the active histone mark H3K4me3." (PMID 26716510, 2016). "We found that the double knockdown suppressed the growth of tumor cells in nude mice to the levels observed with the GATA6 knockdown." (PMID 26387746, 2015). "Since knockdown of GATA6 resulted in a more significant inhibition of tumor growth than REG4 or LGR5 knockdown alone, we examined the effect of REG4 and LGR5 double knockdown on the tumorigenicity of HT29 cells." (PMID 26387746, 2015). "We now provide compelling evidence that GATA6 copy number gain is an additional and recurrent genetic alteration to be considered for this tumor type, and contributes oncogenic signals by virtue of its enhancement of Wnt signaling." (PMID 21811562, 2011). "After 8 weeks, the mean tumor volume was significantly larger in mice injected with Panc1-GATA6 cells than with Panc1-mGATA6 cells, leading us to conclude that GATA6 promotes carcinogenesis via its ability to bind DNA." (PMID 21811562, 2011). "In the morphologically normal epithelia immediately adjacent to tumor areas, both GATA6 and Dab2 are positive." (PMID 19649254, 2009). "Experimental evidence in genetic mouse models has revealed a tumor-suppressive role for GATA6." (PMID 39717718, 2025). "Experiments with xenograft models further confirmed the importance of GATA6 in tumor development." (PMID 40699746, 2025). "The abatement of GATA6 results in an augmented dissemination of tumor cells." (PMID 39717718, 2025). "Targeting EZH2, genetically or pharmacologically, increased GATA6 expression and reduced tumor aggressiveness, suggesting that EZH2 inhibitors could be a therapeutic strategy to induce a less aggressive, more therapy-susceptible PDAC subtype." (PMID 40699746, 2025). "Notably, GATA6 has been designated as a tumor suppressor gene in alternative cellular contexts, with instances of inactivating mutations being identified in human malignant astrocytomas." (PMID 39717718, 2025). "Alongside its role in epithelial cell behavior, GATA6 may enhance anti-tumor immunity, supported by our immune profiling analysis." (PMID 38733987, 2024). "Furthermore, we examined the expression of UTX and UTX-mediated tumor cell aggressiveness with alerted GATA6 expression." (PMID 37692474, 2024). "Fourthly, emphasizing the notable intra-tumoral heterogeneity of GATA6 and classical/basal-like marker expression, our IHC analysis using one slide per tumor may only partially represent GATA6 diversity." (PMID 38733987, 2024).
tumor (continued). "In addition, GATA6 likely plays a role in immune surveillance, a paramount determinant for countering tumor cell dissemination and mitigating metastatic propensity." (PMID 38733987, 2024). "In summary, GATA6 may modulate tumor progression through diverse molecular and biochemical mechanisms, influenced by genetic backgrounds or environmental factors, resulting in either promotion or inhibition." (PMID 38483616, 2024). "Additionally, our results indicated a significant upregulation of miR-181a-5p and downregulation of GATA6 mRNA in tumor tissues of PCa patients." (PMID 38047026, 2023). "Therefore, our results proposed that niraparib mitigated PCa tumor growth in vivo through regulating the MEG3/miR-181-5p/GATA6 axis." (PMID 38047026, 2023). "Moreover, intravital imaging has revealed that peritoneal GATA6 + macrophages upregulate PD-L1 upon taking up apoptotic bodies from tumor cells and promote the growth of CRC liver metastases." (PMID 36737792, 2023). "Interestingly, a recent study showed that peritoneal GATA6 + macrophages invade CRC liver metastases directly from the peritoneal cavity by sensing tumor-induced mesothelial injury." (PMID 36737792, 2023). "In the same tumor samples, opposite results were shown for GATA-6." (PMID 36869369, 2023). "However, further studies are required to understand the origin of the macrophages in ascites from patients with peritoneal metastasis and the regulation of GATA6 expression in PRMs within the tumor environment." (PMID 35401237, 2022). "In the absence of p300, GATA6 expression decreases, leading to dedifferentiation and the loss of dependency on Wnt signaling for tumor maintenance." (PMID 35536676, 2022). "It is proposed that classical tumors follow a default molecular pathway in tumor pathogenesis, as they are the most abundant cell type and display a strong upregulation of transcription factors commonly expressed in normal ductal cells such as GATA6." (PMID 36230515, 2022). "Previous study reported that GATA6 expression was decreased in GC and GATA6 may act as a tumor suppressor." (PMID 35421923, 2022). "GATA6+ PRMs crosstalk with other cell types in the serous cavity, such as stromal cells and T cells, to maintain homeostasis and control the pathological conditions in the event of infection, injury, and tumor metastasis within the serous cavity." (PMID 35401237, 2022). "Thus, GATA4 and GATA5 is currently considered potential tumour suppressors, however, GATA6 can be used as a potential oncogene." (PMID 35488350, 2022). "However, the expression of most of these genes barely changed with BC tumor grade, although GATA6 was upregulated in patients with high-grade BC tumors." (PMID 35729325, 2022). "Therefore, GATA6-mediated tumor angiogenesis should be explored by further laboratory investigations." (PMID 34869004, 2021). "Future ML-powered algorithms may automate tumor cell detection, which could further improve accuracy and precision of GATA6 IHC assessment." (PMID 34294813, 2021). "Recent studies have reported that GATA6 has a basic expression in a variety of tumors, the levels of expression vary significantly depending on the tissue source, and it plays different regulatory roles in the process of tumor development." (PMID 34006300, 2021). "Using this classifier, 57 (44%) baseline tumor samples were GATA6-low and 73 (56%) GATA6-high." (PMID 34294813, 2021). "In a variety of tumor diseases, the role of GATA6 is also complex and varied." (PMID 34006300, 2021). "GATA6 is involved in cell lineage differentiation and organ formation in numerous tissue types and had a contradictory effect on tumor development in accordance with tumor origin." (PMID 34093794, 2021). "Thus, we identified GATA3 and GATA6 as important transcription factors with opposite expression and effects on tumor prognosis in patients with different BLCA stem cell subtypes." (PMID 33115513, 2020).
tumor (continued). "In addition to the tumor-suppressive activity, data also suggests that GATA6 has an oncogenic function." (PMID 32704077, 2020). "Importantly, they found that classical and basal-like programs co-exist within a tumour and demonstrated that molecular subtypes are linked to a specific copy number aberrations in genes such as mutant K-RAS (basal-like subtype) and GATA6 (classical subtype)." (PMID 33371431, 2020). "GATA6 acts as an oncogene or tumour suppressor in different cancers." (PMID 33060563, 2020). "Since GATA6 inhibited tumor formation by inducing cell-cycle arrest and senescence, we manually checked expression level of genes that were reported to be involved in regulation of cell cycle and found that CDKN1A (encoding p21), a potent cell-cycle inhibitor and senescence inducer, was upregulated." (PMID 32596145, 2020). "Here we clarify a tumor suppressive role for GATA6 in NSCLC." (PMID 32596145, 2020). "GATA6 plays an important role in differentiation during the process of embryogenesis, in proliferation during the process of development, and in inhibition apoptosis during the process tumour genesis." (PMID 32757451, 2020). "Knockdown of GATA6 after transplanted KP tumors were fully established (150 mm3) did not cause tumor regression." (PMID 32157212, 2020). "Moreover, suppression of GATA6 induced expression of the Bmp receptor (Bmpr1b) and rendered these tumor cells more sensitive to exogenous Bmp7 stimulation and downstream Smad9 expression." (PMID 32157212, 2020). "For GATA6, both tumor suppressor and proto-oncogene activities have been reported." (PMID 32704077, 2020). "Recent studies have indicated that GATA6 also plays important roles in tumor metastasis." (PMID 30674866, 2019). "Importantly, these infected Mφ were labeled with EGFP, which remained with this Gata6+ cell population throughout our tumor studies." (PMID 29920191, 2018). "We identified very low expression of GATA6 in metastases of malignant LCTs, which might reflect a change in the status in the primary tumour cells promoting invasion." (PMID 29038332, 2017). "GATA6 levels were associated with tumour grade (p=0.005) but not with other clinical–pathological variables." (PMID 27325420, 2017). "To assess the contribution of GATA6 to tumour cell dissemination, we injected GATA6-silenced PaTu8988S and GATA6-overexpressing L3.6pl cells—and the respective control cells—into the spleen of athymic Foxn1nu mice and measured human gene expression in the liver by qPCR, an estimate of dissemination." (PMID 27325420, 2017). "By contrast, a tumour-suppressive function of GATA6 was demonstrated using genetic mouse models." (PMID 27325420, 2017). "We know that GATA6 is a TF particular important in mammalian cell differentiation and molecular programs that mediate normal cell differentiation are required for oncogenesis and tumor cell survival in certain cancers." (PMID 28287094, 2017). "Consequently, the data demonstrate that our tumor cells are well differentiated in which Gata6 remains expressed." (PMID 26716510, 2016). "From these results, we conclude that the epigenetic-driven downregulation of Rbpjl within our carcinogenesis model, which reflects early metaplasia and well-differentiated tumor stages, is independent of a Gata6 loss." (PMID 26716510, 2016). "However, Gata6 was described to have tumor suppressor capacities and an endogenous downregulation was associated with late and poorly differentiated tumor stages." (PMID 26716510, 2016). "Therefore, we stained our tumor cells for Gata6 and E-Cadherin, a marker for epithelial differentiation, and detected high levels of membranous E-Cadherin as well as high levels of Gata6 localized in the nuclei." (PMID 26716510, 2016).
tumor (continued). "In our study, the ability of pulsatile low pH exposure, simulating reflux events, to up-regulate the expression of NR5A2 and GATA6 is suggestive of their role in the mechanism promoting metaplasia and neoplasia in conjunction with epigenetic and polymorphic variation." (PMID 27586588, 2016). "Methylation of the GATA6 has been involved in different cancer types, as lung and ovarian cancer and, in GBM, is considered as a tumor suppressor gene associated with the formation of the tumor." (PMID 22852080, 2012). "Furthermore, in pancreatic orthotopic tumor models, low-grade/well-differentiated tumors not only displayed restricted GATA6 and JUNB expression, but also showed a significantly higher number of GATA6:JUNB double-positive cells compared to high-grade/poorly differentiated tumors." (PMID 39762215, 2025). "Thus, GATA6+ LPM can also become adapted and act as tumor-associated macrophages." (PMID 39192982, 2024). "Therefore, we hypothesized that GATA6 is a potential tumor suppressor gene epigenetically downregulated in HGSOCs." (PMID 37779141, 2023). "Therefore, like PTF1, GATA6 functions as a tumor suppressor in the pancreas." (PMID 37491420, 2023). "Additionally, there is the possibility of sampling error in tumor biopsies, which could lead to mischaracterizations of SMAD4 mutational status or GATA6 mRNA expression." (PMID 38002058, 2023). "In addition, Myc is an oncogene, and Gata6 acts as a tumour suppressor in sebaceous carcinogenesis." (PMID 37735598, 2023). "We also found that the expression of GATA6 in the tumour cells elevated the infiltration of immune cells and the higher expression of GATA6 indicated the poor prognosis of higher infiltration of CTLs and indicated that these genes may involve in the dysfunction of CTLs." (PMID 36336787, 2022). "Using GATA6, miRNA-200 family members, and additional gene products as biomarkers, it may become possible to tailor platinum-based therapies for use only in patients with sensitive tumor cells." (PMID 34944784, 2021). "Hence, in this context, Gata6 functions as a tumor suppressor." (PMID 34888306, 2021). "Analogous to its paradoxical activity in lung development, GATA6 expression fluctuates during different stages of LUAD progression and can epigenetically control diverse transcriptional programs associated with bone morphogenetic protein signaling, alveolar specification, and tumor suppression." (PMID 32157212, 2020). "In addition to MMR regulation, Gata6 may also suppress tumor formation by reducing proliferation and increasing SD/SG differentiation." (PMID 30886049, 2019). "Therefore, we examined the expression of Gata6 in our in vitro pancreatic carcinogenesis model and found unexpectedly an increased gene expression of the acinar transcription factor in 3D-ADMs and in tumor cells." (PMID 26716510, 2016). "Likewise, the role of GATA-6 in neoplasias is controversial." (PMID 18405344, 2008). "This may well be due to stromal signals that induce GATA-6 in the adjacent tumor regions." (PMID 18405344, 2008). "Treatment-induced EMT reduces GATA6+ populations and MHCI expression, which is restored by combining MEKi with HDAC inhibitors, enhancing GATA6+ tumor cells, MHCI, CD8+ T cell infiltration, tumor suppression, and survival." (PMID 41651844, 2026). "Here we show that GATA6 defines a tumor cell state that induces MHCI expression and anti-tumor cytotoxicity upon therapy." (PMID 41651844, 2026). "In vivo, tumors derived from GATA6- or TET1-depleted CAFs exhibited reduced growth, proliferation, and CAF engraftment, underscoring their role in tumor progression." (PMID 40216762, 2025).